NOTCH3 (notch receptor 3)
Diseases named in the same sentence as NOTCH3 in open-access papers (continued):
Sharing a sentence is not in itself a finding about the gene and the disease.
CADASIL (continued). "In 1996, Joutel and colleagues reported the identification of the first genetic locus for stroke, with pathogenic mutations in the NOTCH3 gene [OMIM*600276] observed to cause CADASIL." (PMID 24086431, 2013). "Mutations disrupting human NOTCH3 cause CADASIL, an inherited small vessel disease associated with neurodegeneration and cognitive decline with advanced patient age (Hervé and Chabriat, 2010)." (PMID 23720232, 2013). "Mutations in the human NOTCH3 gene cause cerebral autosomal dominant arteriopathy with subcortical infarcts and leukoencephalopathy (CADASIL)." (PMID 23720232, 2013). "Members of a 5-generational Han Chinese family with CADASIL patients had an R133C mutation in the NOTCH3 gene but only individuals exposed to known vascular risk factors developed CADASIL." (PMID 22623959, 2012). "In this study, we identified a mutation, 475C→T (R133C), in the NOTCH3 gene in a 5-generational Han Chinese family with CADASIL patients." (PMID 22623959, 2012). "Cerebral autosomal dominant arteriopathy with subcortical infarcts and leukoencephalopathy (CADASIL) is an inherited disease with mutations in the NOTCH3 gene." (PMID 22623959, 2012). "Cerebral Autosomal Dominant Arteriopathy with Subcortical Infarcts andLeukoencephalopathy (CADASIL) is a hereditary cerebral arteriopathy caused bymutations in the Notch-3 gene." (PMID 29213795, 2012). "Cerebral autosomal dominant arteriopathy with subcortical infarcts and leukoencephalopathy (CADASIL) is an inherited disease of small arteries caused by mutations in the Notch3 gene." (PMID 22065121, 2012). "Mutations in Notch3 are associated with CADASIL (cerebral autosomal dominant arteriopathy with subcortical infarcts and leukoencephalopathy), a condition that causes recurrent strokes and vascular dementia due to VSMC degeneration." (PMID 23226563, 2012). "Cerebral autosomal dominant arteriopathy with subcortical infarcts and leukoencephalopathy (CADASIL) is an inherited microangiopathy caused by NOTCH3 mutations." (PMID 22367627, 2012). "Other possible candidates include NOTCH3, the causative gene for CADASIL (cerebral autosomal dominant arteriopathy with subcortical infarcts and leukoencephalopathy), and SLC1A3, encoding the EAAT1 (excitatory amino acid transporter and glutamate transporter." (PMID 20969805, 2010). "cerebral autosomal dominant arteriopathy with subcortical infarcts and leukoencephalopathy (CADASIL) is a hereditary brain small vessel disease caused by pathogenic variants in the NOTCH3 gene, leading to NOTCH3 protein accumulation and degeneration of vascular smooth muscle cells (VSMCs)." (PMID 41895274, 2026). "As a model mechanism of action, one of the pathophysiological markers of Cerebral Autosomal Dominant Arteriopathy with Subcortical Infarcts and Leukoencephalopathy (CADASIL) and mutations in the NOTCH3 gene includes an increase in WMHs and a loss of vascular smooth muscle cells." (PMID 39737667, 2025). "Notably, her mother, diagnosed with multiple sclerosis for several decades despite imaging findings suggestive of CADASIL, shares the same NOTCH3 variant." (PMID 40438539, 2025). "Mutations in the NOTCH3 gene have been identified as the major causative factor for CADASIL." (PMID 40470487, 2025). "The prevalence of CADASIL is around 2–5 in 100,000 although recent genomics studies indicate a substantially higher proportion of the population have CADASIL-like NOTCH3 mutations and hence milder forms of inherited small vessel disease may be underdiagnosed." (PMID 40764588, 2025). "In a population study of NOTCH3 variants, only one Caucasian individual in the UK Biobank was found to harbour this variant, however this individual is likely young enough to be asymptomatic as CADASIL is a late-onset disorder." (PMID 41300806, 2025). "CADASIL(Cerebral autosomal dominant arteriopathy with subcortical infarcts and leukoencephalopathy)is an inherited small vessel disease caused by mutations in NOTCH3 gene." (PMID 38408980, 2024).
CADASIL (continued). "While monoallelic cysteine-involving missense variants in NOTCH3 are well-studied in cerebral autosomal dominant arteriopathy with subcortical infarcts and leukoencephalopathy (CADASIL), patients with biallelic variants in NOTCH3 are extremely rare and not well characterised." (PMID 39191170, 2024). "Loss of arterial smooth muscle cells (SMCs) and abnormal accumulation of the extracellular domain of the NOTCH3 receptor (Notch3ECD) are the 2 core features of CADASIL, a common cerebral small vessel disease caused by highly stereotyped dominant mutations in NOTCH3." (PMID 38386425, 2024). "In this study, we focused on in vitro modeling and therapeutic target finding of cerebral autosomal dominant arteriopathy with subcortical infarcts and leukoencephalopathy (CADASIL), the most common form of hereditary stroke disorder caused by mutations in the NOTCH3 gene." (PMID 38592587, 2024). "NOTCH3 cysteine-involving heterozygous variants are well-known to cause cerebral autosomal dominant arteriopathy with subcortical infarcts and leukoencephalopathy (CADASIL) a disease characterised by migraine, dementia, and stroke." (PMID 39191170, 2024). "Considerable focus was given to analyzing Notch3 protein mutations associated with CADASIL disease." (PMID 38790158, 2024). "In contrast, cerebral autosomal dominant arteriopathy with subcortical infarcts and leukoencephalopathy (CADASIL) caused by NOTCH3 is adult-onset and considered to be caused by accumulation of the mutant NOTCH3 extracellular domain (N3ECD) and, possibly, by an impairment in Notch signaling." (PMID 38254727, 2024). "A progressive disease, CADASIL, is associated with vascular abnormalities affecting arterial vascular smooth muscle cells (VSMCs), is an autosomal dominantly inherited disease caused by a NOTCH3 mutation." (PMID 39176342, 2024). "Importantly, we also identified significant accumulation of glycosaminoglycans specifically in the Notch3-deficient model that was also found in patients with CADASIL." (PMID 38015629, 2024). "CADASIL is caused by NOTCH3 mutations on chromosome 19p12.13 with 33 exons." (PMID 39465783, 2024). "CADASIL (cerebral autosomal dominant arteriopathy with subcortical infarcts and leukoencephalopathy) is a hereditary cerebral arteriopathy caused by a neurogenic locus notch homolog protein 3 (NOTCH3) gene mutation." (PMID 37927774, 2023). "CADASIL is caused by mutations of the NOTCH3 gene on chromosome 19." (PMID 37158955, 2023). "Additionally, we found that the set of loss-of-function and cysteine-altering variants present in the causal gene NOTCH3 for the autosomal dominant stroke disorder CADASIL displayed a broad neuro-imaging spectrum." (PMID 37479695, 2023). "Cerebral autosomal dominant arteriopathy with subcortical infarcts and leukoencephalopathy (CADASIL) is the most prevalent hereditary stroke condition attributed to mutations in the neurogenic locus notch homolog protein 3 (Notch-3) gene and serves as a significant contributor to VaD." (PMID 38002991, 2023). "Although genetic mutations in NOTCH3 are prerequisites for CADASIL, the environmental factor may have played an unneglectable role in the onset age and severity of this disease." (PMID 37684694, 2023). "Monogenetic diseases causing ischemic stroke were observed in five patients (2.9%): In three patients with lacunar stroke (1.7%), we identified pathogenic variants in NOTCH3 causing cerebral autosomal-dominant arteriopathy with subcortical infarcts and leukoencephalopathy (CADASIL)." (PMID 36411388, 2023). "In the inherited disease CADASIL (cerebral autosomal dominant arteriopathy with subcortical infarcts and leukoencephalopathy), mutations in NOTCH3 lead to SMC degeneration or pericyte insufficiency, associated with blood vessel thickening and blood flow blockage." (PMID 37601628, 2023). "CADASIL is an autosomal dominant disorder caused by a mutation in the NOTCH3 gene." (PMID 36984587, 2023).
CADASIL (continued). "CADASIL is a disorder marked by stereotyped mutations in NOTCH3, which alter disulfide bonding." (PMID 36470429, 2023). "As pointed out by de Vries in 2014, insights into the genetic basis of migraines may also come from other monogenic syndromes, such as CADASIL, which is caused by mutations in the NOTCH3 gene." (PMID 37873835, 2023). "In this study, we conducted a comprehensive analysis of clinical and imaging features from CADASIL patients in the Japanese population, focusing specifically on individuals harboring the R75P mutation in NOTCH3, and we provided a further understanding of genotype–phenotype association of CADASIL." (PMID 37681004, 2023). "Mutations in the NOTCH3 gene located on the chromosome 19 cause a hereditary stroke disorder known as cerebral autosomal dominant arteriopathy with subcortical infarcts and leukoencephalopathy (CADASIL)." (PMID 36142458, 2022). "CADASIL is caused by a genetic mutation in the NOTCH3 gene, which is present on chromosome 19." (PMID 36465750, 2022). "In regard to human diseases, cerebral autosomal dominant arteriopathy with subcortical infarcts and leukoencephalopathy (CADASIL) is caused by NOTCH3 mutations, and enhanced NOTCH3 expression in SMCs of small arteries in the lung is associated with pulmonary hypertension." (PMID 34990407, 2022). "An important Notch vascular disease is CADASIL, which is caused by NOTCH3 mutations." (PMID 35472289, 2022). "As the most common type of inherited CSVD, cerebral autosomal dominant arteriopathy with subcortical infarcts and leukoencephalopathy (CADASIL) is characterized by the NOTCH3 gene mutation which leads to Notch3 ectodomain deposition and extracellular matrix aggregation around the small vessels." (PMID 36165325, 2022). "Cerebral Autosomal Dominant Arteriopathy with Subcortical Infarcts and Leukoencephalopathy (CADASIL) caused by different types of mutations of Notch 3 gene are associated with extensive cerebral small vessel damage, marked by the accumulation of granular osmiophilic material (GOM)." (PMID 35326259, 2022). "These genes are either associated with non-life-threatening disorders (FLG; ichthyosis vulgaris), late-onset disorders (NOTCH3; cerebral autosomal dominant arteriopathy with sub-cortical infarcts and leukoencephalopathy, CADASIL) or risk factors for disease (PRSS1, CTRC; hereditary pancreatitis)." (PMID 36335097, 2022). "Cerebral autosomal dominant arteriopathy with subcortical infarcts and leukoencephalopathy (CADASIL) is an autosomal dominant inherited cerebrovascular disorder that is an important cause of stroke in young patients caused by mutations in the NOTCH3 gene on chromosome 19." (PMID 36465750, 2022). "Mutations in the NOTCH3 gene are responsible for cerebral autosomal dominant arteriopathy with subcortical infarcts and leukoencephalopathy (CADASIL), adult-onset hereditary angiopathy leading to ischemic episodes, vascular dementia, and other neurologic deficits." (PMID 36544136, 2022). "Finally, the diagnosis of CADASIL was made based on the presence of NOTCH3 mutations in the patient or a third-degree relative." (PMID 35754959, 2022). "Spectrum of NOTCH3 variants found in 38 Chinese CADASIL patients." (PMID 34335700, 2021). "One example is the Notch3 rs201118034 (R544C) mutation, where 0.88% of the people in our cohort carry the mutation but the autosomal dominant condition it causes, CADASIL, has an estimated prevalence in Taiwan of 3.8 in 10,000, which is 23 times lower than expected." (PMID 33574314, 2021). "A pathogenic mutation in NOTCH3 was found to cause cerebral autosomal dominant arteriopathy with subcortical infarcts and leukoencephalopathy (CADASIL), which is clinically characterized by migraine, recurrent subcortical strokes, and vascular cognitive decline or VaD in adults." (PMID 33942994, 2021).
CADASIL (continued). "The Notch signaling pathway has previously been associated with migraine, among others due to the GWAS hit near NOTCH43 and a mutation in NOTCH3 results in CADASIL (cerebral autosomal dominant arteriopathy with subcortical infarcts and leukoencephalopathy) with migraine as one of the main symptoms." (PMID 33859262, 2021). "For example Notch3 is essential for the formation of functional arteries and mature smooth muscle cells, and NOTCH3 mutations cause cerebral autosomal dominant arteriopathy (CADASIL) with severe alterations of small vessel smooth muscle cells in humans." (PMID 31917787, 2020). "The current study analyzed 63 CADASIL patients with genetically confirmed NOTCH3 mutation." (PMID 32321529, 2020). "In 1996, mutations in the NOTCH3 gene were identified as the cause of CADASIL." (PMID 32555735, 2020). "Here, we generated induced pluripotent stem cells (iPSCs) from skin biopsy samples of three CADASIL patients with mutations in the mutational hot spots, exons 2–4 of NOTCH3, and differentiated them into MCs to establish in vitro model for elucidating the pathogenesis of CADASIL." (PMID 32188464, 2020). "Mutations in NOTCH3 have been identified as the underlying cause of cerebral autosomal dominant arteriopathy with subcortical infarcts and leukoencephalopathy (CADASIL), the most common inherited stroke and dementia syndrome in the group of degenerative small vessel diseases." (PMID 32450902, 2020). "Although many studies have attempted to unravel how NOTCH3 mutations lead to artery defects, the pathogenesis of CADASIL is still largely unknown." (PMID 32188464, 2020). "Cerebral autosomal dominant arteriopathy with subcortical infarcts and leukoencephalopathy (CADASIL) is the most common hereditary cerebral small vessel disease caused by mutations in the NOTCH3 gene, leading to devastating disease burden with stroke and vascular dementia in the affected adults." (PMID 32321529, 2020). "Mutations in the NOTCH3 gene on chromosome 19 are believed to be the main cause of CADASIL." (PMID 33352859, 2020). "Cerebral Autosomal Dominant Arteriopathy with Subcortical Infarcts and Leukoencephalopathy (CADASIL) is an inherited disorder caused by a mutation in the NOTCH 3 gene, characterized by early onset of subcortical lacunar infarcts in the absence of vascular risk factors and cerebral microbleeds." (PMID 32128266, 2020). "Characteristics of patients with cerebral autosomal dominant arteriopathy with subcortical infarcts and leukoencephalopathy (CADASIL) and cysteine-sparing NOTCH3 mutations are relatively unknown." (PMID 32555735, 2020). "The low average scores in patients with p.R75P mutations may be due to a lower frequency of temporal pole lesions and older age onset compared with other CADASIL subtypes, such as cysteine-altering NOTCH3 mutations." (PMID 32477100, 2020). "The NOTCH3 p.R75P mutation may be underdiagnosed in patients with early-onset lacunar infarctions due to the atypical clinical and neuroimaging features of CADASIL." (PMID 32477100, 2020). "Cerebral autosomal dominant arteriopathy with subcortical infarcts and leukoencephalopathy (CADASIL) is a genetic paradigm of small vessel disease (SVD) caused by NOTCH3 mutations that stereotypically lead to the vascular accumulation of NOTCH3 around smooth muscle cells and pericytes." (PMID 31753008, 2019). "CADASIL is caused by NOTCH3 mutations that influence vascular smooth muscle cell (VSMC) function through unknown processes." (PMID 31647781, 2019). "Cerebral autosomal dominant arteriopathy with subcortical infarcts and leukoencephalopathy (CADASIL), a hereditary cerebrovascular disease caused by a NOTCH3 gene mutation, has the clinical manifestations of recurrent ischemic stroke, progressive cognitive decline and mental disorders." (PMID 30778920, 2019).
CADASIL (continued). "CADASIL is a small-vessel disease caused by a cysteine-altering pathogenic variant in one of the 34 epidermal growth factor-like repeat (EGFr) domains of the NOTCH3 protein." (PMID 30032161, 2019). "In addition, we report a heterozygous pathogenic gain of cysteine mutation in NOTCH3 (p.R578C) detected in 1 control and already reported in a Korean patient with clinical suspicious CADASIL, implying that the penetrance of NOTCH3 mutations is variable." (PMID 29544907, 2018). "The aim here was to review typical clinical CADASIL syndrome with cysteine-sparing NOTCH3 missense mutations to determine whether they were associated with CADASIL." (PMID 28902129, 2017). "CADASIL (cerebral autosomal dominant arteriopathy with subcortical infarcts and leukoencephalopathy) is caused by mutations in the NOTCH3 gene, affecting the number of cysteines in the extracellular domain of the receptor, causing protein misfolding and receptor aggregation." (PMID 28902129, 2017). "Our data suggested that not only the genetic effects of NOTCH3 gene mutations, but also traditional vascular risk factors (or both of them) might contribute to the pathological changes during the development of CADASIL disease." (PMID 27206574, 2016). "CADASIL has previously been shown to be caused by varying mutations in the NOTCH3 gene." (PMID 27881154, 2016). "Heterozygous NOTCH3 mutations underlie cerebral arteriopathy with subcortical infarcts and leukoencephalopathy (CADASIL, MIM 125310), a disorder of the small arterial vessels of the brain that represents the most common heritable cause of stroke and progressive ischemic dementia in the adults." (PMID 25870235, 2015). "In conclusion, we demonstrated distinct genotypic and phenotypic profiles of CADASIL in Taiwan, where NOTCH3 R544C accounts for approximately 70% of CADASIL which is associated with an older age of onset and a lower percentage of moderate to severe WMLs in the anterior temporal pole." (PMID 26308724, 2015). "CADASIL is caused by the mutations in the NOTCH3 gene (OMIM 600276), which encodes a single pass trans-membrane protein with an extracellular epidermal growth factor-like (EGF-like) repeat domain, a single trans-membrane domain, and an intracellular ankyrin domain." (PMID 25098330, 2014). "In light of the variability among patients and the limitations of currently available NOTCH3 and CADASIL animal models, the mechanism by which NOTCH3 mutations cause CADASIL symptoms – including vascular, white matter and other disease phenotypes – remain to be clarified." (PMID 23720232, 2013). "CADASIL is a vasculopathy of small cerebral and systemic arteries caused by mutations in NOTCH3." (PMID 23720232, 2013). "Cerebral autosomal dominant arteriopathy with subcortical infarcts and leukoencephalopathy (CADASIL) is a rare hereditary systemic vasculopathy, caused by NOTCH3 mutations within the receptor extracellular domain, that lead to abnormal accumulation of the mutated protein in the vascular wall." (PMID 23799141, 2013). "Cerebral autosomal dominant arteriopathy with subcortical infarcts and leukoencephalopathy (CADASIL) is a rare hereditary systemic vasculopathy, caused by mutations in the NOTCH3 gene encoding a transmembrane receptor mainly expressed in vascular smooth muscle cells (VSMC) in adult human tissue." (PMID 23799141, 2013). "Cerebral Autosomal Dominant Arteriopathy with Subcortical Infarcts and Leukoencephalopathy (CADASIL) is the best understood cause of dominantly inherited stroke and results from NOTCH3 mutations that lead to NOTCH3 protein accumulation and selective arterial smooth muscle degeneration." (PMID 23028706, 2012). "Cerebral autosomal dominant arteriopathy with subcortical infarcts and leukoencephalopathy (CADASIL) [MIM 125310] is an autosomal dominant microangiopathy caused by mutations of the NOTCH3 gene that is located on chromosome 19 and encodes a transmembrane receptor." (PMID 22367627, 2012).